IL12B (interleukin 12B)
Diseases named in the same sentence as IL12B in open-access papers (continued):
Sharing a sentence is not in itself a finding about the gene and the disease.
tumor (44 papers, 2016 to 2026). "Activated cDCs in tumours have largely been associated with a core gene expression signature that includes Ccr7 and Il12b, amongst other markers." (PMID 40745918, 2025). "We reveal two distinct cDC1 activation states characterised by differential expression of genes linked to anti‐tumour immunity, including Cxcl9 and Il12b." (PMID 40745918, 2025). "Tumor gene expression analysis performed 7 days post Imprime dosing showed upregulation of M1 markers, e.g., Nos2, Il12b, and Tnfa, along with downregulation of M2-associated genes including Arg1 and Ccl17." (PMID 35692755, 2022). "In the present study, we separately evaluated the tumor expression level of the IL-12 encoding genes IL12B and IL12A." (PMID 31004093, 2019). "In tumor-associated Mφs, the expression of Il12b was facilitated through interactions between BATF2 and the p65/p50 heterodimer, leading to the induction of anti-tumor adaptive immune responses." (PMID 30753547, 2019). "Additionally, we found that stem‐like TCF1+ CD8+ T cells are enriched in tumour‐bordering regions in association with the Il12b/Ccr7‐expressing cDC1s, while effector CD8+ T cells were enriched in the parenchyma in proximity to Cxcl9+ cDC1s." (PMID 40745918, 2025). "Notably, molecular analysis of isolated tumor-infiltrating leukocytes following NI-1701 administration revealed an upregulation of genes linked to immune activation, including IFNγ and IL-12b." (PMID 35538512, 2022). "Strikingly, Il12b‐expressing cDC1s are CCR7+ and enriched at tumour borders, where they closely associate with stem‐like TCF1+ CD8+ T cells." (PMID 40745918, 2025). "Lastly, analysis of a published spatial transcriptomic dataset of human tumours revealed that CCR7+ cDC1s, the human equivalent of the murine Il12b+ cDC1s, are also preferentially associated with TCF1+ T cells as compared with the CXCL9+ cDC1s." (PMID 40745918, 2025). "Proportionally, Cxcl9 cDC1s localised to a greater extent in the parenchyma (CytoMAP Region 6‐infTumour), while the Il12b cDC1s were enriched in tumour border regions (CytoMAP Region 5‐Border)." (PMID 40745918, 2025). "In sum, our results suggest that Cxcl9 and Il12b cDC1s are enriched in different regions of the tumour, with Cxcl9 cDC1s preferentially located in the parenchyma and the Il12b cDC1s in tumour border regions." (PMID 40745918, 2025). "To identify the association of Cxcl9 and Il12b cDC1s with TCF1+ CD8+ T cells, we generated masks representing areas where TCF1+ CD8+ T cells densely accumulate within tumours." (PMID 40745918, 2025). "A significant negative correlation was observed between miR-181a levels and IL6 and IL12B in tumor tissues from patients diagnosed with TNBC." (PMID 37932806, 2023). "Among genes related to inflammation, only Il12b was upregulated in tumor tissue collected from mice that received citrate-coated AgNPs intragastrically." (PMID 37297299, 2023). "Human DC cluster 3 highly expressed the most signatures of mouse Il12b+ DCs and specially appeared in the tumor group." (PMID 37483625, 2023). "The downregulation of the IL6 and IL12B cytokines and the IFNG responses in TNBC tumor samples were associated with significantly poor responses to neoadjuvant therapies that included olaparib." (PMID 37932806, 2023). "In the large majority of tumor types, Il12b, Ifng, Ccl4, Ccl5, Cxcl9, and Cxcl10 showed a significant positive correlation with infiltration of M1 macrophages, with Ccl3 displaying a lesser overall correlation." (PMID 34446712, 2021). "IL-10 is an anti-inflammatory cytokine and interestingly synergizes with IL-12B to regulate inflammation in tumor models." (PMID 34512619, 2021). "Genetic ablation of HO-1 abolished the inhibitory effect of 4T1 tumor cell debris on expression of M1 marker genes, Tnf and Il12b, in LPS-stimulated BMDMs." (PMID 33809707, 2021).
tumor (continued). "The increased presence of MHC-IIhigh macrophages, together with enhanced Il12b and Ifng expression, suggests favorable conditions for the induction of anti-tumor T cell activity in MC38/Nb1 tumors." (PMID 33266104, 2020). "Patients with low tumor tissue IL12B mRNA expression also had a significantly shorter RFS than those with high IL12B (HR = 0.69, 95% CI = 0.50–0.95, p = 0.021 for high vs. low expression)." (PMID 31004093, 2019). "Based on their localisation, Il12b cDC1s might be important to sustain TCF1+ T cells at the tumour border, potentially through local expression of IL‐12, IL‐15 trans‐presentation and/or antigen (cross‐) presentation." (PMID 40745918, 2025). "Two distinct cDC1 activation states are differentially associated with Cxcl9 and Il12b/Ccr7 expression, respectively, each localising to different regions of the tumour, with the Cxcl9+ cDC1s being enriched in the parenchyma while the Il12b+ cDC1s remain located at the edges." (PMID 40745918, 2025). "We found that Cxcl9 and Il12b cDC1s were enriched in different regions of the tumour: Cxcl9 cDC1s were overrepresented in the parenchyma of the tumour, while Il12b cDC1s were located preferentially at the border of the tumour." (PMID 40745918, 2025). "The EV-treated macrophages downregulated expression of M1 polarization-associated genes Cxcl9, Cxcl10 and Il12b, and had reduced capacity to attract activated T cells and to reactivate them to release IFN-γ, key components of an efficacious anti-tumor immune response." (PMID 38389103, 2024). "Moreover, stimulation with mouse-derived recombinant SPP1 protein induced the expression of pro-tumor genes (such as Arg1, Slc2a1, and Nos2) in MDSCs while repressing the expression of anti-tumor genes (such as Il1b, Tnfa, and Il12b)." (PMID 39066845, 2024). "Moreover, pro-inflammation cytokines, such as Il1b, Il12b and Il18, were upregulated in the tumor of Il21r−/− mice; whereas anti-inflammation cytokines, including Il10 and Il22 were decreased in the tumor of Il21r−/− mice." (PMID 38720319, 2024). "The results from MMTV-PyVT mice show that TPPP3+ monocytes, ISG15+ macrophages, IFIT3+ neutrophils, and IL12B+ DCs are mainly present in the tumor-reprogrammed lung microenvironment, and the metastasis-associated myeloid subpopulations are validated at the protein level." (PMID 37483625, 2023). "Notably, the genetic ablation of HO-1 abolished the inhibitory effect of 4T1 tumor cell debris on expression of two representative M1 marker genes, Tnf and Il12b, in LPS-stimulated BMDMs." (PMID 33809707, 2021). "The eight-gene-signature prognostic model (ANGPTL5, CD1B, CD1E, CNTFR, CTSG, EDN3, IL12B, and IL2)-based high- and low-risk groups were significantly related to overall survival (OS), tumor microenvironment (TME) immune cells, and clinical characteristics in LUAD." (PMID 34745015, 2021). "Notably, of the 27 cytokines, we only observe statistically significant HR results for OS according to the low mRNA expression level of IL12B in the tumor tissue." (PMID 31004093, 2019). "Compared to the macrophages in WT group samples, the macrophages isolated from PKN2-WT tumor showed significantly higher expression of Il1b, Tnf, Cxcl9, Il23, Ros1 and Il12b and significantly lower expression of Tgfb1, Vegfa, Egf, Retnla and Il10, illustrating predominant M1 phenotype." (PMID 29368606, 2018). "However, when Tnfsf9 expression at the tumor was combined with rIL-12, survival outcomes were similar across genotypes: 69.2% of Il12b+/+ mice and 63.6% of Il12b−/− mice survived beyond 50 days, indicating that exogenous rIL-12 can compensate for the absence of endogenous IL-12." (PMID 40842154, 2025). "Next, we asked whether Cxcl9 and Il12b cDC1s segregate to different regions of the tumour." (PMID 40745918, 2025).
tumor (continued). "Moreover, IL12B was the single prognostic cytokine with low expression that led to shorter RFS of KRASwt LUAD patients, increasing living risks before tumor recurrence by 1.57 times (HR = 0.638, 95% CI = 0.442–0.921, and p = 0.0166 for the high vs. low IL12B expression KRASwt subgroup)." (PMID 31004093, 2019). "Interestingly, transient increase in the levels of Il12b and Il12rb2 in splenocytes from mice treated with calcitriol and its analogs can contribute to the lack of effect on the Foxp3 expression level during the later stage of tumor progression." (PMID 30037009, 2018). "Network analysis highlighted immune-related hub genes (CXCL1, CCL20, IL12B, and STAT4) involved in chemotaxis, leukocyte migration, and cytokine signaling, linking immune dysregulation to tumor development." (PMID 40445003, 2025). "IFN-γ released after the administration of anti-PD-1/anti-PD-L1 antibodies stimulates DC1s to produce interleukin (IL)-12b, which, in turn, promotes CD8+ T cell activation and tumor control." (PMID 38541099, 2024). "These neutrophils are generated through tumor-specific activation of the STING pathway and can sensitize tumors unresponsive to anti-PD1 therapy, partly via IL12b-mediated activation of cytotoxic T cells." (PMID 38817608, 2024). "mRNA expression of 16 soluble factors was quantified with tumor cell density, and we found that IL-8 was the only factor with fluctuations (HGF, IL-1A, and IL-12B expression levels were extremely low)." (PMID 36932390, 2023). "CDH17 ‘high-methylation’ cases, showed increased expression of IL12B, IL10, CXCL9 and 10 and CCL2 compared to CDH17 ‘low-methylation’ cases, suggestive of a favourable cytokine/chemokine ‘milieu’ in these tumours." (PMID 36612154, 2022). "Objective response rate (complete or partial response) was significantly correlated to tumor microenvironment-related SNPs concerning CCL2, NOS3, IL1RN, IL12B, CXCR3, and IL6R genes." (PMID 32733486, 2020). "Our PCR array data showed that both M1-related genes (Ccl2, Ccl3, Ccl4, Ccl5, Il12b, Il1b and Ccl1) and M2-related genes (Il10, Tgfb2 and Il1rn) were significantly upregulated in NM11-shsST2 tumours compared with NM11-shCont tumours." (PMID 27882929, 2016). "In Il12b+/+ mice that did not receive rIL-12, Tnfsf9 expression by the tumor cells significantly extended median survival by 27 days compared with CT-2A-FLuc-null control condition." (PMID 40842154, 2025). "Importantly, we identified several lymphocyte activation ligands that were significantly upregulated on Ccr7_DC.2 versus other tumour CCR7+ DC states and Kaede-red dLN CCR7+ DCs, such as Il12b, Tnfsf4, Tnfsf9, Cd70 and Pvr." (PMID 38267413, 2024). "The inverse correlation was stronger (ρ = -0.44; p < 0.01) when the combined expression levels of IL12B and SHBG were considered, suggesting that inhibition of apoptosis may be a further downstream mechanism that mediates the tumor promoting activity of IL30." (PMID 38087324, 2023). "Importantly, the prognostic significance of IL12B was further strengthened by its ability to stratify within many currently known prognosticators, including gender (female), age at diagnosis (>65 for OS), tumor stage I, with EGFR mutation, and without KRAS mutation." (PMID 31004093, 2019). "Thus, potential interactions between Il12b cDC1s and stem‐like TCF1+ CD8+ T cells, as well as Cxcl9 cDC1s and effector TCF1− CD8+ T cells, might be important for anti‐tumour immunity across species." (PMID 40745918, 2025). "Using isolated tumor tissue, we analyzed gene expression related to cytotoxicity (Perforin, Granzyme B, Granulysin, and FasL), inflammatory or chemotactic cytokines (IFN-γ, CXCL9, CXCL10, and CXCL11), and CD8+ T cell activation and proliferation (CD69, Tbx21, IL-2, and IL-12b)." (PMID 39066478, 2024).
tumor (continued). "Then, we performed immunofluorescence staining on the normal lung, primary tumor, and metastatic lung sections using the markers of Tppp3+ monocytes (LY6C and TPPP3), Isg15+ macrophages (F4/80 and ISG15), Ifit3+ neutrophils (MPO and IFIT3), and Il12b+ DCs (CD11c and IL12B)." (PMID 37483625, 2023). "Similarly, bosentan treatment led to no significant changes in the mRNA levels of Chitinase, IL12B, ETA and ETB in tumor associated macrophages (TAMs) as compared to TAMs isolated from placebo treated tumors." (PMID 36241617, 2022). "Its induction in the presence of ascites could be due to an effect on monocytic cells that were freshly recruited to the tumor microenvironment and thus not yet strongly affected by ascites, or the effect of ascites on IL12B could be of a reversible nature." (PMID 29997615, 2018). "Ly6Ehi neutrophils are induced by tumor-intrinsic activation of the STING (stimulator of interferon genes) signaling pathway and possess the ability to directly sensitize otherwise non-responsive tumors to anti-PD1 therapy, in part through IL12b-dependent activation of cytotoxic T cells." (PMID 38181798, 2024).
cancer (16 papers, 2014 to 2025). A tumor composed of atypical neoplastic, often pleomorphic cells that invade other tissues. "Their pooled data indicated that IL-12B rs3212227 polymorphism was associated with cancer risk in overall." (PMID 34837895, 2021). "One of the cancer-risk loci frequently identified was the SNP rs3212227 in IL12B, which shows significant association to overall cancer risk, especially among Asians, and, particularly, to hepatocellular and nasopharyngeal cancer." (PMID 33408595, 2020). "Single Nucleotide Polymorphisms (SNP) in the IL-12 genes, IL12A and IL12B, have been reported to modulate cancer risk across different populations and cancer types." (PMID 32973967, 2020). "A high number of studies have evaluated the relationship of the rs3212227 SNP in IL12B with cancer risk." (PMID 32973967, 2020). "In the past years, we considered only IL-12B polymorphism played an important role in cancer development and looked down on the function of IL-12A." (PMID 28415696, 2017). "The IL-12B gene encodes a subunit common to interleukin IL-12 and IL-23, both of which protect against infectious diseases and cancer." (PMID 24728409, 2014). "Among them, IL-6R, IL-8, IL-10RB, IL-12A, and IL-12B was significantly associated with the prognosis of cancer consistent to our finding." (PMID 25075970, 2014). "The IL-6R, IL-8, IL-10RB, IL-12A, and IL-12B was associated with the prognosis of cancer in data of both our study and a previous study." (PMID 25075970, 2014). "In the other types of cancer studies, IL-6R, IL-8, IL-10RB, IL-12A, and IL-12B genes were consistently associated with cancer prognosis between our study and theirs." (PMID 25075970, 2014). "IL-12B rs3212227 was proved to enhance overall cancer risk (C vs. A: OR = 1.15, 95%CI: 1.05-1.25; CC vs. AA: OR = 1.32, 95%CI: 1.11-1.56; AC vs. AA: OR= 1.21, 95%CI: 1.08-1.35, P = 0.001; AC+CC vs. AA: OR = 1.24, 95%CI: 1.10-1.40, P < 0.001; CC vs. AC+AA: OR = 1.17, 95%CI: 1.04-1.31)." (PMID 28415696, 2017). "Ultimately, 33 studies with 10,587 cancer cases and 12,040 cancer-free controls were elected in this meta-analysis to explored the relationship of IL-12A rs568408 (10 studies), IL-12A rs2243115 (9 studies), and IL-12B rs3212227 (30 studies) polymorphisms and cancer risk." (PMID 28415696, 2017). "Among them, HLA-DMB, HLA-DRA, IL12A, and IL12B, whose determinant role in cancer outcome as immune adjuvants has already been published, are found in the top 500 TG2 positively correlating genes." (PMID 35725560, 2022). "The IL12B gene, which codes for the IL12 p40 subunit has been the most studied IL-12 related-gene in cancer genetic association analyses." (PMID 32973967, 2020). "In fact, both IL-12A and IL-12B gene have played a role in the development of cancer." (PMID 28415696, 2017). "Among these, ‘proteoglycans in cancer’ (P = 0.0040) and ‘NF-kappa B signaling pathway’ (P = 0.0316), involving TLR2, TLR4 and IL-12B genes, were our main focus due to their roles in immunity response." (PMID 31337442, 2019). "In cancer, SNPs in IL12A and IL12B may alter protein expression or function, contributing to immune dysregulation and increased oncogenic risk." (PMID 40519922, 2025).
immune disorders (5 papers, 2011 to 2024). "IL-12B polymorphisms have been reported to be associated with several immune disorders." (PMID 24859272, 2014).
infectious disease (5 papers, 2011 to 2025). A disorder directly resulting from the presence and activity of a microbial, viral, or parasitic agent in humans. "Both amount and variability of cytokine synthesis are genetically regulated by single nucleotide polymorphisms (SNPs) in IL-12 A and IL-12B; these also influence susceptibility to infectious diseases, disease severity, as well as the response to antiviral treatment." (PMID 41272580, 2025).
IL12B also shares sentences with these, for which no sentence is quoted: diabetes (5 papers); bacterial infection (4); ovarian tumors (3); chronic obstructive pulmonary disease (2); colon adenocarcinoma (2); Mendelian susceptibility to mycobacterial diseases (2); nasopharyngeal carcinoma (2); primary biliary cholangitis (2); schistosomiasis (2); Acanthamoeba keratitis (1); age (1); AIDS (1); Alzheimer disease (1); amyloid (1); anaemia (1); aortic regurgitation (1); atopic asthma (1); bacteremia (1); bipolar disorder (1); bronchogenic carcinoma (1); candidiasis (1); celiac disease (1); chronic kidney disease (1); cognitive decline (1); cutaneous vasculitis (1); dementia (1); depression (1); diabetic eye disease (1); Erythema nodosum (1); gastric tumor (1).
A further 40 diseases each share a sentence with IL12B in 1 paper.